IGF1R (insulin like growth factor 1 receptor)
Diseases named in the same sentence as IGF1R in open-access papers (continued):
Sharing a sentence is not in itself a finding about the gene and the disease.
pancreatic cancer (129 papers, 2007 to 2025). "In contrast, the increase in IGF1R expression in cells with a lower level of IGFBP-3 expression was associated with more advanced pancreatic cancer and worsened the prognosis." (PMID 31565100, 2019). "In contrast, circulating levels of IGF-I and IGF-II are associated with benefit from IGF-1R inhibitors in the treatment of pancreatic cancer." (PMID 26991655, 2016). "In patients with several cancers including pancreatic cancer, high expression of IGF-1R in tumors is associated with higher tumor grades and poor survival." (PMID 25638159, 2015). "3-Cl-AHPC stimulated miR-150* expression and caused decreased expression of c-Myb and IGF-1R in the pancreatic cancer cells." (PMID 23675407, 2013). "The IGF-1R signaling cascade has been implicated in the development and progression of pancreatic cancer, and naturally, both preclinical and clinical studies directed at this pathway have been initiated." (PMID 24212944, 2011). "IGF-1R has also been implicated in pancreatic cancer, and it has been speculated that it is regulated by several microRNAs including miR-7, miR-139, miR-145 and miR-1." (PMID 41153350, 2025). "Pancreatic cancer cells’ resistance to ONC201 has been linked to strong IGF1-R expression." (PMID 41020897, 2025). "Resveratrol exerts potent anticancer effects in part by targeting the insulin-like growth factor 1 receptor (IGF-1R), a key mediator of pancreatic cancer growth and metastasis." (PMID 40918466, 2025). "When ONC201/ONC212 was combined with AG1024 (an IGF1-R inhibitor), this combination exhibited synergism in in vitro and in vivo models of pancreatic cancer." (PMID 41020897, 2025). "Soft agar experiments demonstrated that inhibiting IGF‐1R prevents pancreatic cancer cells from forming colonies in vitro." (PMID 39434498, 2025). "Overall, our results point to a crucial role of Fra-2 in the cellular stress response due to nutrient restriction typical of pancreatic cancer and support IGF1R as a promising and vulnerable target in miR-15a downmodulated PDAC." (PMID 38342897, 2024). "The setbacks in clinical trials targeting IGF1R in pancreatic cancer have raised critical questions about the complexities of the IGF system in the clinical context." (PMID 39087024, 2024). "Insulin-like growth factor-1 receptor (IGF1R) is a tyrosine kinase receptor that is usually highly expressed in pancreatic tumors and stromal cells and lowly expressed in normal pancreatic tissues." (PMID 38338418, 2024). "This feature makes IGF1R a potential target for therapeutic strategy targeting pancreatic cancer and its stroma." (PMID 38338418, 2024). "The cytostatic effect of IGF1R knockdown agrees with previous findings in gastric, breast and pancreatic cancer." (PMID 34554347, 2022). "The in vitro pancreatic cancer cell line data suggests that IGF1R signaling is required to induce a phenotypic switch of cells that possess low CD44 expression to one that shows a high level of CD44 expression with CD44s being the predominant isoform." (PMID 35931675, 2022). "Fortunately, linsitinib (OSI-906), a novel dual IR/IGF-1R inhibitor, showed a good effect in treating pancreatic cancer." (PMID 35252207, 2022). "Treatments targeting uPAR in human pancreatic cancer cells inhibit the migration and invasion of mouse tumour cells mediated by c-met and insulin like growth factor 1 receptor (IGF1R)." (PMID 35303878, 2022). "And clinical trials of linsitinib showed a prolonged overall survival of in advanced high IGF-1R expression solid tumors (including lung cancer, melanoma, pancreatic cancer, and gastrointestinal stromal tumors)." (PMID 35252207, 2022). "This study suggests that IGF1R-dependent CD44 isoform switching confers pancreatic cancer cells to undergo an adaptive change in response to gemcitabine and provides the basis for improved targeted therapy of pancreatic cancer." (PMID 35931675, 2022).
pancreatic cancer (continued). "Based on these findings, the prognostic significance of CD44 and IGF1R expression in tumors from patients with pancreatic cancer were analyzed using the TCGA pancreatic cancer dataset." (PMID 35931675, 2022). "The increased insulin density in the pancreatic cancer microenvironment and IR overexpression in cancer cells finally lead to the failure of IGF-1R inhibitor in pancreatic cancer trials." (PMID 35252207, 2022). "Increased gemcitabine sensitivity in GR cells using a different IGF1R inhibitor, picropodophyllin which inhibited cell viability in the pancreatic cancer cells." (PMID 35931675, 2022). "c-Myb, IGF-1R and Bcl-2 that are over-expressed in pancreatic cancer cells have a controlling role in cell proliferation, apoptosis, and differentiation." (PMID 33849540, 2021). "The IGF1/IGF-1R signaling axis was also shown to promote the survival of dormant pancreatic cancer cells after oncogenic KRAS or MYC ablation in pancreatic cancer cells." (PMID 33807785, 2021). "With regard to many cancer entities—including colorectal or pancreatic cancer—the IGF1R was assigned the role of the villain." (PMID 34638472, 2021). "A previous study showed the negative regulation between miR-150-3p and IGF1R in pancreatic cancer cells." (PMID 33723215, 2021). "Inhibition of GIPC shows anticancer effects on pancreatic cancer in vitro and in vivo, together with a reduction in the levels of insulin-like growth factor 1 receptor (IGF1R)." (PMID 32756339, 2020). "In pancreatic cancer, hypoxic conditions both induce IGF-1 expression in cancer-associated fibroblasts (CAFs) and the IGF-1R expression in pancreatic cancer cells, and such IGF-1R signaling promotes cell mobility." (PMID 33511137, 2020). "To determine the role of Ajuba in SP1-mediated transcriptional regulation, we examined the mRNA level of the best known SP1target genes EGFR and IGF1R in pancreatic cancer Patu8988 cells used for cell growth assays by using qRT-PCR approach." (PMID 31101117, 2019). "Clinical trials are ongoing using small molecule-targeting protein kinase D, which is involved in pancreatic cancer, and insulin-like growth factor-1 receptor (IGF-1R) that is involved in MAPK and PI3K/Akt pathways and also cross-talks with EGFR pathway." (PMID 31277491, 2019). "Most recently, FOXC1 was identified as a downstream mediator of insulin-like growth factor 1 receptor (IGF1R) signaling in pancreatic cancer, where it promotes EMT and metastasis in vivo." (PMID 30764547, 2019). "Recently, we reported that IGF-1R is aberrantly overexpressed in pancreatic cancer cells favoring tumor cell survival, epithelial-to-mesenchymal transition (EMT), and metastatic pathways." (PMID 29976975, 2018). "The outcomes of these focused preclinical studies have been positive, whereas clinical trials of IGF-1R inhibitors in pancreatic cancer have failed, raising the questions about this therapeutic approach." (PMID 29976975, 2018). "The previous study from our lab demonstrated that IGF-1R was upregulated in pancreatic cancer and contributes to its progression and metastasis." (PMID 29976975, 2018). "To understand the influence of IGF-1R on TFs in pancreatic cancer, we used the Transcription Factor Activation Profiling Array and examined the activation levels of various TFs in IGF-1R-silenced HPAC cells." (PMID 29976975, 2018). "IGF-1R signaling controls various vital cellular functions and this signaling is deregulated in many cancers, including pancreatic cancer." (PMID 29976975, 2018). "There is evidence of abnormal, pro-tumorigenic and pro-survival IGF1-R signaling in several cancers including pancreatic cancer." (PMID 29137221, 2017). "A recently published research suggests that stroma-derived IGFs can blunt the response to chemotherapy in pancreatic cancer via an IGF-insulin/IGF1R paracrine signaling axis." (PMID 28969062, 2017). "Targeting IGF1-R has previously shown therapeutic benefit by blunting pancreatic cancer growth and metastasis." (PMID 29137221, 2017).
pancreatic cancer (continued). "For example, levels of the IGF ligands predict benefit from the IGF-1R monoclonal antibody ganitumab in pancreas cancer supporting the idea that receptor activation is an important predictive biomarker for anti-IGF-1R drugs." (PMID 26991655, 2016). "Hematoxylin & eosin staining of tissue samples and immuno fluorescence staining confirmed the expression of IGF-1R in the pancreatic cancer tissues." (PMID 26919100, 2016). "Western blotting showed Panc-1, BxPC-3, and MIA PaCa-2 pancreatic cancer cell lines expressed IGF-1R." (PMID 26919100, 2016). "Labeling with fluorophore-conjugated IGF-1R antibody demonstrated fluorescent foci on the membrane of the pancreatic cancer cells." (PMID 26919100, 2016). "In the present study, we demonstrate that fluorescent anti-IGF-1R antibodies target pancreatic cancer in orthotopic mouse models enabling non-invasive imaging and high resolution intra-vital imaging of the tumor." (PMID 26919100, 2016). "The present study demonstrates that fluorophore-conjugated IGF-1R antibodies can visualize pancreatic cancer and it can be used with various imaging devices such as endoscopy and laparoscopy for diagnosis and fluorescence-guided surgery." (PMID 26919100, 2016). "There is also a report that the expression of IGF-1R in pancreatic cancer is higher than in normal pancreas." (PMID 26919100, 2016). "Since IGF-1R is very frequently expressed in pancreatic cancer, and its expression is stronger than in the normal pancreas, detecting IGF-1R can be used for diagnosis purposes." (PMID 26919100, 2016). "Western blotting confirmed the expression of IGF-1R in Panc-1, BxPC3, and MIAPaCa-2 human pancreatic cancer cell lines." (PMID 26919100, 2016). "Using four PDAC cell lines and two pancreas cancer-associated fibroblasts (CAFs), the expression of insulin-like growth factor-1 (IGF1) and IGF1 receptor (IGF1R) was evaluated by RT-PCR, FACScan, western blot, or ELISA." (PMID 27487118, 2016). "IGF1R level of pancreas cancer cells, RWP-1, OCUP-AT, and MiaPaCa-2 cells, were significantly high in hypoxia, in compared with that in normoxia, but that of Panc-1 did not significantly increase under hypoxia." (PMID 27487118, 2016). "Clinico-pathological analyses showed that 17.4% of surgical pancreatic cancer specimens were quadruple-positive for IGF-1R, EP2 (or EP4), MAP4K3, and PKC-θ." (PMID 25638159, 2015). "In vitro studies have shown that exogenous IGF-1-stimulated growth of pancreatic cancer cell lines is abrogated following treatment with anti-IGF1R antibodies." (PMID 25638159, 2015). "In the present study, we checked for the presence of alternative signaling interactions between EPs and IGF-1R mainly in pancreatic cancer cells using selective antagonists against EP2 and EP4." (PMID 25638159, 2015). "GIPC1 was shown to bind to IGF-1R via its PDZ domain in order to promote pancreatic cancer cell proliferation." (PMID 26209534, 2015). "An aberrant regulation of IGF-1R enables MIA PaCa-2 pancreatic cancer cells to escape rapidly from quiescence, makes them growth factor independent, and promotes survival during unfavorable conditions." (PMID 25944691, 2015). "Overall, our results demonstrate the crosstalk between EP2/EP4 and IGF-1R signaling mainly in pancreatic cancer cells that produce and secrete PGE2." (PMID 25638159, 2015). "In the present study, we characterized a novel interaction between EP2/EP4 and IGF-1R signaling pathways mainly in pancreatic cancer cells." (PMID 25638159, 2015). "The plasma levels of IGF-1R in patients with pancreatic cancer, chronic pancreatitis, other pancreatic tumors, PNET and healthy volunteers were 0.823±0.57 ng/ml, 0.472±0.42 ng/ml, 0.562±0.3 ng/ml, 0.460±0.21 ng/ml, 1.004±0.50 ng/ml, respectively." (PMID 24667580, 2014). "Matrigel invasion, transwell migration and wound healing assays also revealed a role for IGF-1R in metastatic properties of pancreatic cancer." (PMID 24809702, 2014).
pancreatic cancer (continued). "The classic wound healing assay was performed to test the role of IGF-1R in regulating the migratory ability of pancreatic cancer cells." (PMID 24809702, 2014). "The anti-proliferative effect of targeting IGF-1R is highly significant in both of the highly aggressive pancreatic cancer cell lines." (PMID 24809702, 2014). "In conclusion, we demonstrated that miR-497 attenuated the malignancy of pancreatic cancer cells and promoted sensitivity of cells to gemcitabine by directly downregulation of IGF-1R expression." (PMID 24667580, 2014). "In our study, reduced COX-2 and pSTAT3 expression achieved by IGF-1R inhibition indicates the potential role of IGF-1R in inflammation mediated carcinogenesis of pancreatic cancer." (PMID 24809702, 2014). "Silencing the expression of IGF-1R in pancreatic cancer cells inhibits their growth and metastasis and the beneficial effects of calorie restriction in pancreatic cancer models appear mediated through the IGF-1/IGF-1R axis." (PMID 25295009, 2014). "Here, we observed the induction of apoptosis at a high frequency in IGF-1R silenced pancreatic cancer cells with increasing time of transfection." (PMID 24809702, 2014). "We also found aberrantly over expressed IGF-1R in pancreatic cancer cell lines (PANC-1 and HPAC) and in human pancreatic adenocarcinoma tissues." (PMID 24809702, 2014). "Silencing IGF-1R dramatically reduced the colony forming capacity in both pancreatic cancer cell lines." (PMID 24809702, 2014). "This strongly indicates that blocking IGF-1R expression suppresses the migrating abilities of both aggressive pancreatic cancer cell lines." (PMID 24809702, 2014). "We showed that plasma IGF-1R displayed a value for distinguishing pancreatic cancer from chronic pancreatitis and PNET (AUC = 0.713, 95% CI: 0.564–0.862, P = 0.008; AUC = 0.711, 95% CI: 0.581–0.840, P = 0.009, respectively)." (PMID 24667580, 2014). "Our present study focuses on defining the role of IGF-1R in pancreatic cancer and lays a strong foundation for the deeper and broader understanding of the molecular mechanisms by which IGF-1R contributes to PDAC pathogenesis." (PMID 24809702, 2014). "Upregulation of miR-497 in BxPC-3 and AsPC-1 pancreatic cancer cell lines inhibited proliferation, enhanced apoptosis, re-sensitized cells to gemcitabine and suppressed IGF-1R and p-AKT expression through direct downregulation of IGF-1R protein expression." (PMID 24667580, 2014). "Plasma IGF-1R levels in pancreatic cancer patients increased, and displayed potential values for distinguishing pancreatic lesions." (PMID 24667580, 2014). "Our results demonstrate that silencing of IGF-1R inhibits metastasis of pancreatic cancer cells by enhancing the expression of E-cadherin." (PMID 24809702, 2014). "Cell monolayers were scratched to create a wound to monitor the migrating ability of both control and IGF-1R suppressed pancreatic cancer cells." (PMID 24809702, 2014). "In vitro matrigel invasion assays using transwell Boyden chambers which mimic the internal basement membrane of the tumor microenvironment were used to investigate the invading potential of IGF-1R siRNA transfected pancreatic cancer cells." (PMID 24809702, 2014). "We found that silencing IGF-1R inhibits pancreatic cancer growth and metastasis by blocking key signaling pathways such AKT/PI3K, MAPK, JAK/STAT and EMT." (PMID 24809702, 2014). "Silencing IGF-1R decreased the viability of pancreatic cancer cells at 48 h post-transfection compared with scrambled siRNA transfected control cells." (PMID 24809702, 2014). "Currently mTOR is considered as one of the potential alternative targets for PDAC treatment and is also considered as a master regulator similar to what we show here for IGF-1R in pancreatic cancer." (PMID 24809702, 2014). "Results from three independent experiments were quantified, which reveals >85% inhibition of colony forming capability in IGF-1R silenced pancreatic cancer cells." (PMID 24809702, 2014).
pancreatic cancer (continued). "Our study showed that plasma IGF-1R levels in patients with pancreatic cancer increased significantly, compared with that in patients with chronic pancreatitis, other pancreatic tumors and PNET." (PMID 24667580, 2014). "Clinical studies in colorectal, esophageal, and pancreatic cancers have shown that IGF1R signaling correlates with increased tumor growth and malignancy in vitro." (PMID 23962053, 2013). "Clinicopathological features of 122 patients with curatively resected pancreatic cancer were retrospectively reviewed, and expression of IGF1R and IGFBP3 was immunohistochemically analyzed." (PMID 23962053, 2013). "Inhibition of IGF-1R utilizing small molecule kinase inhibitors has resulted in reduced pancreatic cancer growth." (PMID 23675407, 2013). "The present study examined IGF1R and cell surface-associated IGFBP3 expression in patients with pancreatic cancer." (PMID 23962053, 2013). "Overexpression of miR-630 also induced apoptosis in the pancreatic cancer cells and inhibited target protein IGF-1R mRNA and protein expression." (PMID 23675407, 2013). "Together these results implicate key roles for miR-150* and miR-630 and their targeting of IGF-1R to promote apoptosis in pancreatic cancer cells." (PMID 23675407, 2013). "Specifically, we've shown that up-regulation of miR-150* and miR-630 is important to the inhibition of IGF-1R, which inhibits growth and induces apoptosis in pancreatic cancer cells." (PMID 23675407, 2013). "We have previously shown that knock down of IGF-1R expression reduced pancreatic cancer cell proliferation while also enhancing 3-Cl-AHPC-mediated apoptosis." (PMID 23675407, 2013). "3-Cl-AHPC-induced apoptosis was preceded by decreasing expression of IGF-1R, cyclin D1, β-catenin, and activated Notch-1 in the pancreatic cancer cell lines." (PMID 22570653, 2012). "3-Cl-AHPC exposure on pancreatic cancer cells decreased expression of IGF-1R, cyclin D1, and β-catenin prior to the inhibition of proliferation and the induction of apoptosis." (PMID 22570653, 2012). "We found that IGF-1R was significantly expressed in the pancreatic cancer sphere cells and its expression was markedly inhibited by exposure to 3-Cl-AHPC." (PMID 22570653, 2012). "IGF-1R signaling regulates proliferation, invasion, and angiogenic growth factor expression by pancreatic cancer cells." (PMID 22570653, 2012). "Decreased IGF-1R expression inhibited the growth of the PANC-1 pancreatic cancer cells and increased the 3-Cl-AHPC-mediated inhibition of CD44+/CD24+sphere size." (PMID 22570653, 2012). "3-Cl-AHPC and AHP3 exposure on the expression of cyclin D1, β-catenin, and IGF-1R in the pancreatic cancer cells was assessed." (PMID 22570653, 2012). "IGF-1 and its receptor IGF-1R play a major role in proliferation, invasive potential, and metastatic behavior of pancreatic cancer cells." (PMID 22570653, 2012). "Further studies have documented that IGF-1/IGF-1R-mediated enhanced pancreatic carcinoma proliferation and invasiveness requires an interaction between IGF-1R and the hepatocyte growth receptor c-Met." (PMID 22570653, 2012). "Among carcinomas, IGF-1R targeting has been most widely evaluated in breast, lung, colon, and pancreatic cancer and numerous reviews have outlined its impact, or absence thereof, in detail elsewhere." (PMID 24212944, 2011). "This Akt effect on IGF-1R has been suggested to be responsible for the invasiveness of pancreatic cancer cells." (PMID 21422497, 2011). "Pancreatic cancer cells have elevated IGF-1R expression and it is well known that Akt regulates IGF-1R expression." (PMID 21422497, 2011). "Though it is too early to judge of the efficacy of IGF-1R therapies, alone or in combination with other targeted agents in pancreatic cancer, preliminary results suggest they're relatively well tolerated even in patients with advanced cancer stage." (PMID 24212944, 2011).